WSB2 (WD repeat and SOCS box containing 2)
Description:
May be a substrate-recognition component of a SCF-like ECS (Elongin-Cullin-SOCS-box protein) E3 ubiquitin ligase complex which mediates the ubiquitination and subsequent proteasomal degradation of target proteins.
Synonyms: SBA2; MGC10210; LAGNS
Tractability: PROTAC: its protein half-life has been measured.
Gene: Protein-coding gene on chromosome 12 (118,032,687 to 118,062,430, reverse strand). Ensembl gene ENSG00000176871.
Pathways (Reactome):
Metabolism of proteins: Neddylation
Gene Ontology:
Molecular function: protein binding
Biological process: protein polyubiquitination; intracellular signal transduction; protein ubiquitination
Cellular component: cytosol
Genetic constraint (gnomAD): Loss-of-function variants: 11 observed, 50.09 expected, observed/expected ratio (o/e) 0.22, 90% interval 0.14 to 0.36. The upper end of that interval is the gene's LOEUF score, 0.36, which puts it in group 1 of 6, group 1 being the genes least tolerant of losing a copy. Missense variants: 315 observed, 529.44 expected, observed/expected ratio (o/e) 0.59, 90% interval 0.54 to 0.65. Synonymous variants: 190 observed, 212.11 expected, observed/expected ratio (o/e) 0.9, 90% interval 0.8 to 1.01.
Homologues: Orthologues: chimpanzee WSB2 (99% identical), macaque WSB2 (99% identical), pig WSB2 (98% identical), dog VSIG10 (98% identical), guinea pig WSB2 (97% identical), rabbit WSB2 (97% identical), mouse Wsb2 (96% identical), rat Wsb2 (94% identical), tropical clawed frog wsb2 (72% identical), zebrafish wsb2 (44% identical). Paralogues in human: WSB1 (50% identical).
Diseases named in the same sentence as WSB2 in open-access papers:
WSB2 is named in the same sentence as 24 diseases in open-access papers, as found by Europe PMC text mining. Sharing a sentence is not in itself a finding about the gene and the disease. The quoted sentences say what the papers report.
breast carcinoma (4 papers, 2023 to 2025). "In breast cancer, miR-28-5p inhibited breast cancer cell migration through the regulation of WSB2, whereas in colorectal cancer (CRC), reduced expression of CUL9 has been reported to inhibit CRC cell growth." (PMID 41200507, 2025). "Increased levels of this miRNA lead to downregulated expression of WSB2, which induces breast cancer cell migration." (PMID 40563399, 2025). "In breast cancer, overexpression of WSB2 may promote MCF-7 cell migration, whereas miR-28-5p inhibits the migration of breast cancer cells by regulating WSB2 expression." (PMID 37647033, 2023). "Upregulation of WSB2 expression in breast cancer may correlate with low levels of miR-28-5p." (PMID 40563399, 2025). "Thus, the miR-28-5p/WSB2 axis may represent a novel therapeutic target in breast cancer." (PMID 37647033, 2023).
melanoma (4 papers, 2023 to 2024). A malignant, usually aggressive tumor composed of atypical, neoplastic melanocytes. "WSB2 (WD repeat and SOCS box containing protein 2), as an E3 ubiquitination enzyme, has been demonstrated to play a key role in the proliferation of melanoma." (PMID 36866240, 2023). "The research results of our group showed that WSB2 was significantly increased in melanoma and promoted the proliferation and migration of melanoma cells." (PMID 36866240, 2023). "A previous study showed that WSB2 could activate the Wnt/β-catenin signalling pathway and promote the proliferation of melanoma cells." (PMID 36866240, 2023). "WSB2 levels were upregulated in patients with melanoma or breast cancer, and there is no report about the effects of WSB2 in HCC." (PMID 38177295, 2024).
liver cancer (2 papers, 2024 to 2025). An epithelial or non-epithelial malignant neoplasm that arises from the liver. "Consistent with WSB2 mRNA expression in the liver cancer (LIHC) cohort in the UALCAN database and Gene Expression Omnibus (GEO) database, WSB2 expression was markedly increased in HCC tumor tissues compared to the matching adjacent normal liver tissues at both the mRNA level and protein level." (PMID 38177295, 2024).
developmental delays (1 paper, 2026). "In summary, our study provides evidence that recessive WSB2 variants result in a new neurodevelopmental disorder characterized by global developmental delays, hypotonia, seizures, abnormal brain morphology, dysmorphic features, and failure to thrive." (PMID 40374945, 2026).
Failure to thrive (1 paper, 2026). Failure to thrive (FTT) refers to a child whose physical growth is substantially below the norm. "Similarly, the low birth weight and failure to thrive phenotype seen in three of the five patients (P:1, P:2 and P:5) carrying homozygous pLoF variants was also seen in both male and female Wsb2-mutant mice." (PMID 40374945, 2026).
hepatocellular carcinoma (1 paper, 2024). A malignant tumor that arises from hepatocytes.
male infertility (1 paper, 2025). The inability of the male to effect fertilization of an ovum after a specified period of unprotected intercourse. "However, recent large-scale mouse phenotype analyses conducted by the International Mouse Phenotyping Consortium (IMPC) have reported abnormalities in tooth morphology, locomotor activity, retina, heart, osmotic and electrolyte balance, as well as male infertility in Wsb2−/− mice." (PMID 40699886, 2025).
malignant peripheral nerve sheath tumor (1 paper, 2025). Malignant peripheral nerve sheath tumor (MPNST) is a rare and often aggressive soft tissue sarcoma occurring in a wide range of anatomical sites. "Although Wsb2 depletion did not induce apoptosis in RPE1 cells, DepMap data revealed that peripheral nervous system (PNS) tumors, including neuroblastomas or malignant peripheral nerves sheath tumors (MPNSTs), are sensitive to Wsb2 depletion." (PMID 40832228, 2025). "The Cancer genetic dependencies data from The Cancer Map Dependency Project (DepMap) show that tumors of the nervous system, Neuroblastomas and Malignant Peripheral Nerve Sheath Tumors (MPNSTs), are over-represented amongst those in which Wsb2 is essential for viability." (PMID 40832228, 2025).
neuroblastoma (1 paper, 2025). Neuroblastoma (NB) is the most common solid, extracranial childhood tumor. "Taken together, our data are consistent with loss of Wsb2 causing cell death by initiating apoptosis in Neuroblastomas." (PMID 40832228, 2025). "We show loss of Wsb2 in neuroblastoma cells leads to a sudden and dramatic increase in apoptosis, suggesting that Wsb2 is a strong candidate for drug discovery in this class of cancers." (PMID 40832228, 2025). "First, we designed constitutively expressed shRNAs against Wsb2 and introduced them into the Neuroblastoma cell lines CHP134 and TGW." (PMID 40832228, 2025). "Finally, we demonstrate that Wsb2 is essential in Neuroblastoma cell lines and protects cells from apoptosis induction, highlighting its potential as a therapeutic target." (PMID 40832228, 2025). "While Wsb2 is not essential in most primary or tumor cells, high-throughput DepMap data suggest it is critical for survival in tumors of the peripheral nervous system, such as neuroblastoma." (PMID 40832228, 2025).
Obesity (1 paper, 2024). Accumulation of substantial excess body fat. "The increased incidence of excessive alcohol consumption or obesity in young patients may also be responsible for the increased expression of WSB2." (PMID 38177295, 2024).
PNS) tumors (1 paper, 2025). "= 0.471) between the essentiality of Wsb2 and Bcl2l2 in PNS tumors." (PMID 40832228, 2025).
prostate adenocarcinoma (1 paper, 2025). "Relationship between WSB2 mRNA expression and Gleason score (B), pathological T stage (C), clinical T stage (D), and nodal metastasis status (E) in prostate adenocarcinoma (PRAD) patients from the TCGA cohort." (PMID 40699886, 2025). "Remarkably, WSB2 mRNA levels were significantly elevated in multiple cancers, including prostate adenocarcinoma (PRAD) and liver hepatocellular carcinoma (LIHC), compared to corresponding normal tissues." (PMID 40699886, 2025).
cancer (8 papers, 2021 to 2026). A tumor composed of atypical neoplastic, often pleomorphic cells that invade other tissues. "Previous studies on WSB2 have primarily concentrated on its expression in cancer tissue and cells, as well as its roles in carcinogenesis." (PMID 40374945, 2026). "While COMMD2, WSB2, and CUL9 have been implicated in various cancers, their roles in LSCC remain underexplored." (PMID 41200507, 2025). "WSB2 is frequently overexpressed in cancers such as lung, breast, and melanoma, where it promotes malignancy by driving cell proliferation, cycle progression, and migration." (PMID 40699886, 2025). "Next, we observed a significant increase in NOXA protein levels upon WSB2 silencing across various cancer cell lines, including Huh7, H1299, and A549." (PMID 39866840, 2025). "To explore the clinical relevance of WSB2, we analyzed its expression across various human cancer types using RNA-sequencing (RNA-seq) data from The Cancer Genome Atlas (TCGA)." (PMID 40699886, 2025). "Despite the fact that WSB2 is upregulated in various types of cancer and exhibits a strong anti-apoptotic function, which makes it a promising target for cancer therapy, it is crucial to comprehensively understand the downstream substrates regulated by the CRL5WSB2 E3 ligase complex." (PMID 40699886, 2025). "Further investigation is needed to determine whether WSB2 dysregulation is responsible for the accelerated protein turnover observed in various cancer types, such as MCL and CD adenomas." (PMID 40699886, 2025). "Collectively, these data suggest that WSB2 overexpression is a common feature in several aggressive cancers and may contribute to tumor progression, metastasis, and resistance to therapy." (PMID 40699886, 2025). "WSB2 is an E3 ubiquitin ligase and also crucial in cellular cancers." (PMID 41200507, 2025). "Moreover, WSB2 is overexpressed in several human cancer types." (PMID 40699886, 2025). "Targeting both WSB2 and anti-apoptotic BCL-2 family proteins holds promising therapeutic potential for overcoming resistance in human cancers." (PMID 40699886, 2025). "Collectively, these data indicate that co-targeting WSB2 and anti-apoptotic BCL-2 family proteins triggers synthetic lethality in cancer cells." (PMID 40699886, 2025). "In a large-scale RNAi screening aimed at understanding cancer dependencies and synthetic lethal relationships, the top correlates of WSB2 co-essentiality were found to be MCL-1, BCL-2, and MARCH5, while the most strongly anti-correlated gene with WSB2 was BAX." (PMID 40699886, 2025). "COMMD2, WSB2 and CUL9 contribute significantly to many cancers or tumors." (PMID 41200507, 2025). "Our findings suggest that disrupting the WSB2–NOXA axis could synergize with BCL-2 inhibitors to induce apoptosis in cancer cells, offering a novel strategy for combating apoptosis resistance in human cancers." (PMID 40699886, 2025).
tumor (6 papers, 2022 to 2026). "Other genes, such as ARPC3, POLR2H, WSB2, and ARL6IP5, show opposite association with response in tumor and stroma compartments, respectively." (PMID 41550766, 2026). "(A) WSB2 mRNA expression in normal and tumor tissues from the The Cancer Genome Atlas (TCGA) cohort." (PMID 40699886, 2025). "Through a combination of cell line studies, xenograft tumor models, and knockout mice experiments, we investigated the biological significance and therapeutic potential of targeting WSB2." (PMID 40699886, 2025). "High WSB2 expression was positively correlated with large tumor size (p < 0.001), vascular invasion (p = 0.036), distant metastasis (p = 0.047) and advanced TNM stage (p < 0.001)." (PMID 38177295, 2024). "Herein, we report a new E3 ligase, WSB2, that is highly expressed in HCC and is associated with aggressive tumor phenotypes and a poor prognosis." (PMID 38177295, 2024). "Overexpression of WSB2 significantly increased the orthotopic liver tumor volume and tumor weight compared to controls." (PMID 38177295, 2024). "WSB2 promotes HCC cell proliferation, migration and invasion in vitro and promotes tumor growth and lung metastasis in vivo." (PMID 38177295, 2024).
neurodevelopmental disorder (1 paper, 2026). A behavioral and cognitive disorder with onset during the developmental period that involves impaired or aberrant development of intellectual, motor, or social functions. "Our findings suggest that homozygous LoF WSB2 variants cause a novel neurodevelopmental disorder in humans with similar neurologic and developmental findings seen in Wsb2-mutant mouse models." (PMID 40374945, 2026). "In this study, we present five patients with neurodevelopmental disorders (NDDs) associated with extremely rare variants in WSB2, encoding a CRL substrate receptor (SR) not previously linked to human disease." (PMID 40374945, 2026).
WSB2 also shares sentences with these, for which no sentence is quoted: colorectal cancer (2 papers); ciliopathy (1); colon cancer (1); intrauterine growth restriction (1); microcephaly (1); Neurodevelopmental delay (1); pancreatic cancer (1); prostate carcinoma (1); tumors of the nervous system (1).